APOE (apolipoprotein E)
Diseases named in the same sentence as APOE in open-access papers (continued):
Sharing a sentence is not in itself a finding about the gene and the disease.
Alzheimer disease (continued). "While LA and ARA are substrates for the synthesis of bioactive oxylipins, some investigators suggest ω6 DPA may improve blood lipids, i.e., LDL-C and HDL-C as well as neural inflammation in an APOE-based Alzheimer’s disease model." (PMID 37819925, 2023). "Here, we use summary statistics from five GWAS of Alzheimer’s disease to develop PRSs with and without inclusion of single nucleotide polymorphisms (SNPs) from the APOE gene region." (PMID 37649099, 2023). "Alzheimer’s disease is associated with various factors, including APP, PSEN1, PSEN2, and APOE." (PMID 37240173, 2023). "Although APOE ɛ4 has been identified as the strongest genetic risk factor for Alzheimer’s Disease, there are some APOE ɛ4 carriers who do not go on to develop Alzheimer’s disease or cognitive impairment." (PMID 37198167, 2023). "In both analyses, each region has three stages of increasing abnormality relative to a control group that is expected to be at minimal risk of Alzheimer’s disease (in both cases: amyloid-negative, APOE ε4−, cognitively normal participants)." (PMID 37433038, 2023). "APOE e4 carriers tended to be more frequent in Alzheimer’s disease patients (P = 0.077)." (PMID 37680670, 2023). "In order to utilize polygenic risk scores (PRSs) for Alzheimer’s disease (AD) in a meaningful way, influential factors (i.e. training set) and prediction across groups such as APOE e4 (APOE4) genotype as well as associations to dementia-related biomarkers should be explored." (PMID 37516890, 2023). "In addition, the binding of endotoxins to Apolipoprotein E (APOE) causes a variation in APOE4 and exacerbates the endotoxin production, promoting susceptibility to Alzheimer’s disease." (PMID 36829474, 2023). "In addition, since there are APOE alleles, the normal types E3 and E4, with a higher risk of Alzheimer’s disease, we analyzed the differences between TOMM40-APOE3 and TOMM40-APOE4." (PMID 38201273, 2023). "Hence, our model can provide valuable insights for researchers studying neurodegeneration and the role of ApoE ε4 in Alzheimer’s disease." (PMID 37947590, 2023). "Similarly, APOE‐ε4 non‐carriers in highest quintile of the PRS had a significantly higher probability of Alzheimer's disease than those in the lowest PRS quintile between ages 70 and 85 (difference of 6.7% at age 70 to 30.5% by age 85)." (PMID 36946865, 2023). "However, the threshold difference between amyloid positivity and negativity is only 10–20% and fluctuates with circadian rhythms, aging, and APOE‐ε4 during the decades of evolution of Alzheimer's disease." (PMID 37013968, 2023). "Visuospatial and constructional skills may be impaired as early as at the age of 11–16 years if an individual has both positive APOE ε4 and a family history of Alzheimer’s disease." (PMID 37239094, 2023). "The APOE locus has been associated with increased vulnerability to severe COVID-19 and mortality, especially for the APOE4 homozygous genotype (ε4/ε4), which is the strongest genetic risk factor for sporadic Alzheimer’s disease." (PMID 36371754, 2023). "One of the main genes responsible for brain dyslipidaemia in Alzheimer’s disease is APOE." (PMID 37189413, 2023). "Besides, top 20 genes with high GDA scores, including ApoE, were further investigated for their involvement in Alzheimer’s disease through a literature review." (PMID 40809494, 2023). "However, most GWAS signals do not present large enough effect sizes to be translated into drug targets, apart from some notable exceptions, such as APOE for Alzheimer’s disease." (PMID 38254924, 2023). "Mendelian randomization analyses suggested causal roles for several proteins, for example, ApoE, CD33, and GRN in Alzheimer's disease, MMP‐10 in preclinical Alzheimer's disease, SIGLEC9 in amyotrophic lateral sclerosis, and CD38, GPNMB, and ADAM15 in Parkinson's disease." (PMID 36504281, 2023).
Alzheimer disease (continued). "In an effort to determine whether magnitude of VSI is a novel and early biomarker of mild stage Alzheimer’s disease, the current study will also assess plasma-based total and phosphorylated Tau, neurofilament (NfL) and (ApoE)." (PMID 37065459, 2023). "The APOE gene is another major factor in Alzheimer’s disease." (PMID 37240173, 2023). "For cognitive function, differences in cognitive scores per 1-SD decrease ApoE were obtained for subscale of the Alzheimer Disease Assessment Scale (ADAS-cog) and Modified Mini-Mental State Examination (3MSE) in all subjects from linear regression using the same covariates." (PMID 37666928, 2023). "In addition, when the model was also adjusted for APOE status, an increased risk was observed for CSF AA3 concentrations compared to the overall Alzheimer’s dementia analysis." (PMID 37258587, 2023). "Among individuals with Alzheimer's disease (AD), APOE e4 carriers with increased white matter hyperintensities (WMHs) may selectively be at increased risk of cognitive impairment." (PMID 36864910, 2023). "We then tested for differences in demographic and apolipoprotein E (APOE) ε4 status between these subtypes to better understand their relationship to Alzheimer’s disease and primary age-related tauopathy (PART15), the latter being characterized by age-related tau in the MTL in the absence of Aβ." (PMID 37433038, 2023). "Because APOE-ε4 is also a robust predictor of dementia diagnosis, including Alzheimer’s disease, it is, however, unknown if the link between all-cause mortality, cause-specific mortality, and APOE-ε4 is mediated by dementia diagnosis in older adults." (PMID 37434484, 2023). "However, we found the overall penetrance of Alzheimer's disease in the highest quintile of the PRS to be identical to the penetrance of the APOE‐ε4 alone." (PMID 36946865, 2023). "The major complement regulator, factor H, binds Aβ‐associated apoE isoforms apoE2 and apoE3 but not the Alzheimer's disease‐associated isoform apoE4." (PMID 37155564, 2023). "The apolipoprotein E4 (APOE4) genotype is predictive of Alzheimer’s disease (AD)." (PMID 37432149, 2023). "Interestingly, it has also been shown that Apolipoprotein E (ApoE), an apolipoprotein involved in lipid and cholesterol transport and Alzheimer’s disease, specifically the isoforms E3 and E4, can bind and repress ApoD expression." (PMID 37237893, 2023). "We included 60 MCI patients with APOE ε3/ε3, 18 MCI patients with APOE ε2/ε3, 73 CN subjects with APOE ε3/ε3, and 36 CN subjects with APOE ε2/ε3 genotypes who had resting‐state functional magnetic resonance imaging data from the Alzheimer's disease Neuroimaging Initiative." (PMID 36468416, 2023). "To determine whether KL-VShet+ mitigates Alzheimer’s disease (AD) progression, we used longitudinal linear-mixed models to compare the rate of change in multiple cognitive measures in AD patients stratified by APOE ε4 carrier status." (PMID 37107675, 2023). "The apolipoprotein E4 (APOE4) genotype is the strongest prevalent genetic determinant of Alzheimer’s disease (AD) risk with heterozygotes (APOE3/E4) and homozygotes (APOE4/E4) carriers at 3–4- and 12–15-fold increased risk, respectively, relative to the “wild-type” APOE3/E3 genotype." (PMID 37432149, 2023). "In CN samples, interestingly, among the most significant pathways enriched with significant CpGs is the KEGG pathway “Alzheimer’s disease”, which was curated based on recent AD literature and included genes that confer AD risks, such as APOE, PSENEN, MAPT, CALM3, MME, and others." (PMID 37038196, 2023). "The apolipoprotein E (APOE) gene is the strongest genetic risk factor for Alzheimer’s disease (AD); however, how it modulates brain homeostasis is not clear." (PMID 37605285, 2023). "Polygenic risk scores (PRSs) can boost risk prediction in late-onset Alzheimer’s disease (LOAD) beyond apolipoprotein E (APOE) but have not been leveraged to identify genetic resilience factors." (PMID 35879306, 2022).
Alzheimer disease (continued). "In conclusion, in the context of a Swedish twin study, the APOE region explains much of the measured genetic contribution to Alzheimer’s disease, with smaller contributions from other measured polygenic influences, yet much of the background genetic liability to risk is unexplained." (PMID 35169705, 2022). "APOE genotyping for 11 participants did not demonstrate a difference between responders and non-responders in genetic predisposition toward developing Alzheimer's disease." (PMID 35903111, 2022). "The increased levels of apoE secreted by apoE2-expressing microglia may suppress inflammation in a paracrine manner to protect against Alzheimer’s disease." (PMID 36077289, 2022). "The presence of the rs10423769_A allele reduces the odds ratio for Alzheimer disease risk from 7.2 for ApoE ε4/ε4 carriers lacking the A allele to 2.1 for ApoE ε4/ε4 carriers with at least one A allele." (PMID 35788729, 2022). "In Alzheimer’s disease patients, BNP levels are also higher in those that carry an APOE e4 allele." (PMID 35942230, 2022). "In addition to apolipoprotein E, there were 27 additional proteins whose levels varied according to low versus high polygenic score for Alzheimer’s disease at a Bonferroni corrected p-value 1.5 x 10−5 (0.05/ 3231)." (PMID 36048760, 2022). "Apolipoprotein E4 (APOE4) is associated with a greater response to neuroinflammation and the risk of developing late-onset Alzheimer’s disease (AD), but the mechanisms for this association are not clear." (PMID 35705959, 2022). "The absolute risk of dementia associated with predictors characteristic of Alzheimer’s disease was greater in women than men while at the same time the combination of APOE ɛ4 non-carrier with normal amyloid was more protective in women than men." (PMID 35310829, 2022). "Apolipoprotein E (APOE) is a gene that encodes a cholesterol transporter, and the ε4 allele is associated with higher circulating cholesterol levels, greater burden of cortical ß-amyloid plaques, and elevated risk for Alzheimer’s disease (AD)." (PMID 35404972, 2022). "Furthermore, data supporting a relationship between APOE ε4, myo-inositol and Alzheimer’s disease pathology (amyloid-beta and tau proteins) in the preclinical stage of Alzheimer’s disease are limited." (PMID 35702728, 2022). "The ApoE ε2 allele is associated with the recessive inheritance of hyperlipoproteinemia in patients with type III hyperlipidemia, and the ε4 allele is strongly associated with cardio-cerebrovascular diseases and Alzheimer’s disease." (PMID 36012187, 2022). "The major genetic risk factor linked to Late-Onset Alzheimer’s Disease (LOAD) is the presence of one or two copies of the ε4 allele in the APOE gene, but this is neither a necessary nor sufficient condition for developing the disease." (PMID 35456392, 2022). "Interestingly, Butovsky’s group identified a specific apolipoprotein E (APOE)-dependent molecular signature in microglia from mouse models of multiple amyotrophic lateral sclerosis and Alzheimer’s disease." (PMID 36411434, 2022). "Apolipoprotein E, as a component of lipoprotein, may disrupt the blood-brain barrier (BBB) and increase the risk of Alzheimer’s disease (AD)." (PMID 36742201, 2022). "Although the age-of-onset distributions for Alzheimer’s disease have been well-established since 1993, the basis of this distribution was only partially explained by the apolipoprotein E (APOE) genotype, suggesting that other genetic factors must contribute to age-of-onset for the disease." (PMID 35034660, 2022). "An XGBoost model achieved an AUC of 0.60 to 0.74, depending on the various combinations of feature vectors, such as demographics, APOE genotype, cognitive and functional measures from the Trial-Ready Cohort in Preclinical/Prodromal Alzheimer’s Disease (TRC-PAD)." (PMID 35207561, 2022).
Alzheimer disease (continued). "Moreover, the APOE ɛ4 genotype, known to exacerbate beta amyloid pathology in Alzheimer’s disease, has been suggested to play a role in accelerated cognitive decline in PD." (PMID 36245388, 2022). "Possession of the Apolipoprotein E allele 4 (APOE4), the strongest known genetic risk factor for sporaidc Alzheimer’s disease (AD), may influence the relationship between cardiovascular and brain health." (PMID 35802628, 2022). "In addition to Alzheimer’ disease, apoE also plays a role in other neurodegenerative diseases, such as Parkinson’s disease." (PMID 36077289, 2022). "The possible explanation is that Alzheimer’s disease is highly heterogeneous and fish oil supplements may interact with apolipoprotein E (APOE) genotype and stage of Alzheimer’s disease pathologic changes." (PMID 36161159, 2022). "rs439401 is also associated with lower risk of Alzheimer’s disease, and appears to be functionally independent of another APOE SNP (rs429358) which is the most widely studied Alzheimer’s disease variant (R2 ~ 0.1)." (PMID 36088317, 2022). "Moreover, the usage of different promoters has been described for genes involved in Alzheimer’s disease, such as apolipoprotein E gene (APOE) and the presenilin-2 gene (PSEN2)." (PMID 35203451, 2022). "Further, APOE protein expression levels in specific brain regions seem to add to the development of Alzheimer’s disease and may therefore possibly also contribute to decline in general cognitive function." (PMID 36446774, 2022). "Despite inconsistent reports of ApoE’s role in ALS, it is possible that the ApoE-4 allele is a genetic risk factor and the ApoE-2 allele is a genetic protective factor for disease development, similar to the situation with Alzheimer’s disease." (PMID 35840315, 2022). "Molecular docking results suggest that 5,6-DMI may exhibit inhibitory activity against apoE protein and may act as potential against Alzheimer's disease." (PMID 35128106, 2022). "The apolipoprotein E gene (APOE), which is the most important genetic risk factor for late-onset Alzheimer’s disease, has also been shown to be associated with a risk of early-onset Alzheimer’s disease." (PMID 36077172, 2022). "Neither sample size, adjustment for ApoE ε4, baseline cognition nor education significantly moderated the association between PA and Alzheimer’s disease incidence." (PMID 35301183, 2022). "The SNP in APOE with the lowest P value for association with LST is rs429358, for which the C allele associated with lower LST was previously associated with higher self-reported MVPA13 and forms part of the Ɛ4 risk allele for Alzheimer’s disease (Discussion)." (PMID 36071172, 2022). "The overall m6A level was elevated in the cortex and the hippocampus of APP/PS1 (Alzheimer’s disease) mice compared to C57BL/6 control mice, and FTO was found to interact with APOE, which was associated with Alzheimer’s disease risk in a prospective cohort study." (PMID 36407103, 2022). "ApoC1 and ApoE SNPs on TOMM40 are associated with longevity and Alzheimer’s disease risk." (PMID 36233190, 2022). "Sex and the apolipoprotein E (APOE) isoform APOE4, a risk factor for developing Alzheimer's disease, might contribute to these divergent data." (PMID 36353888, 2022). "However, only 5–10% of patients with early-onset Alzheimer’s disease are carrying a pathogenic mutation in APP, PSEN1, PSEN2, or the common apolipoprotein E (APOE) ɛ4 allele." (PMID 36077172, 2022). "Recently, metabolomics has been used to study the mechanisms involved in the genetic dependence of different ApoE subtypes in Alzheimer’s disease, but there is still a lack of adequate research data on ApoE-deficient disease models." (PMID 36139057, 2022). "Therefore, the implications of the APOE genotype in inflammatory eye-related diseases and their connection to the development of Alzheimer’s disease are highly relevant." (PMID 36153580, 2022).
Alzheimer disease (continued). "Apolipoprotein E (APOE) genotype is well-known to be related to late onset Alzheimer’s disease." (PMID 36092303, 2022). "Therefore, we suggest that myo-inositol is a candidate in vivo marker to study the impact of APOE ε4 on the interplay between astrocytes and the pathophysiology of Alzheimer’s disease." (PMID 35702728, 2022). "The APOE e4 allele has been linked to poorer cognitive performance and greater cognitive decline in older adults, and APOE e4 may increase vulnerability to cognitive effects of Alzheimer’s disease (AD) pathology." (PMID 36312032, 2022). "This may reflect that those two neurodegenerative disorders have strong signals (e.g., APOE region for Alzheimer's disease) that were removed by the quality control preprocessing within GENESIS." (PMID 33098356, 2022). "In the current study, our finding that levels of APOE were increased in individuals with a high polygenic score served as a useful positive control, given the well-documented role of APOE in the pathophysiology of Alzheimer’s disease." (PMID 36048760, 2022). "Liver-generated plasma apolipoprotein E (apoE) does not enter the brain but nonetheless correlates with Alzheimer’s disease (AD) risk and AD biomarker levels." (PMID 35418601, 2022). "Consent for APOE genotyping should always be obtained from patients prior to completing genotyping, as they would incidentally also be learning about other disease risks, including Alzheimer's disease." (PMID 35237638, 2021). "Across the entire cohort, the levels of pTau and Aβ showed expected differences for brain region (higher levels in temporal cortex), neuropathological diagnosis (higher in participants with Alzheimer's disease), and APOE genotype (higher in participants with one or more APOE ε4 allele)." (PMID 33796061, 2021). "For example, several genes causing ALS and/or frontotemporal dementia (C9orf72, VCP, SQSTM1, OPTN, UBQLN2, GRN, CHMP2B) affect the autophagic machinery; and some Alzheimer’s Disease genes (APOE, TREM2, CD33, ABCA7) are preferentially or exclusively expressed in microglia." (PMID 33892821, 2021). "In addition, this APOE-by-sex interactive effect is more evident in medial temporal regions known to succumb to Alzheimer’s disease early." (PMID 34189460, 2021). "The prognostic value of brain network change is independent of Alzheimer’s disease (AD)-related genetic risk (APOE status), the presence of AD-associated pathology (cerebrospinal fluid phosphorylated tau, cortical amyloid) and cortical thinning." (PMID 35382259, 2021). "Compared with non-carriers, carriers of the ε4 allele of the APOE gene have been shown to be associated with a higher risk of developing Alzheimer’s disease in late-onset families." (PMID 34177454, 2021). "Age, sex and APOE status are the strongest predictors of Alzheimer’s disease, warranting the search for sensitive MRI markers to detect brain changes that may indicate later vulnerability to disease." (PMID 33615215, 2021). "An absence of astrocyte-derived ApoE and the expression of ApoE4, a chief genetic risk factor for Alzheimer's disease leads to a compromised BBB." (PMID 33878948, 2021). "The highest PPR was seen in APOE E4/E4 subjects compared to E4/E3 and E3/E3, consistent with prior work, as the effect of APOE and amyloid beta burden on accelerated cognitive and clinical decline in both Alzheimer’s disease and cognitively normal subjects is well-established." (PMID 34704025, 2021).